ENSG00000260836 (novel protein)
Gene: Protein-coding gene on chromosome 15 (82,536,788 to 82,573,194, reverse strand). Ensembl gene ENSG00000260836.
Genetic constraint (gnomAD): Loss-of-function variants: 1 observed, 62.4 expected, observed/expected ratio (o/e) 0.016, 90% interval 0.005 to 0.076. Missense variants: 458 observed, 756.64 expected, observed/expected ratio (o/e) 0.61, 90% interval 0.56 to 0.65. Synonymous variants: 277 observed, 283.73 expected, observed/expected ratio (o/e) 0.98, 90% interval 0.88 to 1.08.